APOA5 (apolipoprotein A5)
Diseases named in the same sentence as APOA5 in open-access papers (continued):
Sharing a sentence is not in itself a finding about the gene and the disease.
Insulin resistance (11 papers, 2014 to 2025). Increased resistance towards insulin, that is, diminished effectiveness of insulin in reducing blood glucose levels. "Taken together these data demonstrate a novel role for ApoA5 as a modulator of susceptibility to liver and muscle insulin resistance through regulation of ectopic lipid accumulation in liver and skeletal muscle." (PMID 25548259, 2015). "HFD-fed ApoA5 ASO-treated mice were protected from HFD-induced insulin resistance, as assessed by hyperinsulinemic-euglycemic clamps." (PMID 25548259, 2015). "In contrast, liver ceramide content was increased in ApoA5 ASO-treated mice compared with control ASO-treated mice despite protection from lipid-induced hepatic insulin resistance in these mice." (PMID 25548259, 2015). "To assess the potential role of ApoA5 on whole-body energy metabolism and lipid-induced insulin resistance, we fed mice RC or HFD and decreased hepatic ApoA5 expression by ASO treatment for 8 weeks." (PMID 25548259, 2015). "Moreover, the prevalence of hyperglycemia was increased in the Q1 of the ApoA5 level, suggesting that ApoA5 is closely related to insulin resistance, which may be probably attributed to the potent effect of ApoA5 on TG." (PMID 35854768, 2022). "The protection from HFD-induced insulin resistance in ApoA5 ASO-treated mice could be partially attributed to enhanced peripheral insulin sensitivity, as evidenced by increased peripheral glucose uptake and increased 2-deoxyglucose uptake in skeletal muscle and WAT." (PMID 25548259, 2015). "Recently, apolipoprotein AV (APOAV), also served as the APOA5, has been found to be a novel apolipoprotein and to play a key role in the processes of insulin resistance and lipid metabolism." (PMID 32382544, 2020). "In order to understand the mechanism by which ApoA5 ASO-treated mice were protected from lipid-induced liver and muscle insulin resistance, we assessed DAG and ceramide content, nPKC translocation, and insulin-stimulated AKT2 phosphorylation in these tissues." (PMID 25548259, 2015). "Notably, two significant genome-wide SNPs, rs662799 in APOA5 and rs671 in ALDH2, were identified exclusively in the overweight/obese group, suggesting a stronger genetic contribution to insulin resistance in this population." (PMID 40699860, 2025). "In order to test this hypothesis, we examined the impact of knocking down hepatic ApoA5 expression by targeted antisense oligonucleotide (ASO) treatment on diet-induced hepatic steatosis and liver and muscle insulin resistance in awake mice." (PMID 25548259, 2015). "In humans, apoA5 could be internalized by human adipocytes primarily via binding to LRP1, and the uptake of apoA5 was attenuated in obese adipose tissues and in cultured adipocytes with hypertrophy or insulin resistance." (PMID 30053818, 2018).
familial chylomicronemia syndrome (8 papers, 2020 to 2025). A rare autosomal recessive disease characterized by the buildup in the blood of fat particles called chylomicrons (chylomicronemia), severe hypertriglyceridemia, and the risk of recurrent and potentially fatal pancreatitis and other complications. "At the genetic level, severely elevated triglyceride levels resulting from familial chylomicronemia syndrome (FCS) are caused by homozygous or biallelic loss-of-function variants in LPL, APOC2, APOA5, LMF1, and GPIHBP1 genes." (PMID 32793115, 2020). "Familial chylomicronemia syndrome (FCS) is a rare disorder of triglyceride (TG) metabolism caused by loss of function variants in one of five known canonical genes involved in chylomicron lipolysis and clearance—LPL, APOC2, APOA5, LMF1, and GPIHBP1." (PMID 38974610, 2024). "Recently, we developed Apoa5 knockout (Apoa5−/−) golden hamster model that reproducibly exhibited severe HTG, closely resembling human familial chylomicronemia syndrome." (PMID 41409096, 2025). "When due to very rare monogenic mutations in the genes encoding the enzyme, lipoprotein lipase, or its regulators, APOC2, APOA5, GPIHBP1, and LMF1, it is referred to as the familial chylomicronemia syndrome." (PMID 33193106, 2020).
breast carcinoma (7 papers, 2013 to 2024). "Moreover, alterations in APOA5 can elevate the risk of developing breast cancer." (PMID 38676834, 2024). "We further examined the prognostic values of the mRNA expressions of APOA1, APOC3, APOA4, and APOA5 by using two online survival analysis software packages that were established through analyses of predominantly Western patients with breast cancer." (PMID 34226567, 2021). "In contrast, the linkage among APOA1 rs670, APOC3 rs2854116 and APOC3 rs2854117 was lost in breast cancer patients, while significant linkage was only observed between the two APOA5 SNPs (D’=1.00)." (PMID 23829168, 2013). "The distributions of the tested SNPs (APOA1 rs670, APOC3 rs2854116, APOC3 rs2854117, APOA5 rs662799 and APOA5 rs2075291) fitted the Hardy-Weinberg equilibrium in both breast cancer patients and healthy controls." (PMID 23829168, 2013). "The results showed that 5 genes, APOA5, CCDC28B, CCL5, SERPINA12, and WT1, were significantly overexpressed in breast cancer patients (P < 0.05)." (PMID 38676834, 2024). "Comparative analysis with the well-established MCF-10A reference cell line revealed a significant upregulation of APOA5, CHAC1, EMID1, GOSR2, TCP1, and TMEM167A in breast cancer cell lines." (PMID 38300336, 2024). "Considering the association of the constituent genes of the GRS formula with luminal breast cancer, such as APOA5 and DUX4, the limitations of its application in non-luminal breast cancer can be taken into account." (PMID 39151519, 2024).
acute pancreatitis (6 papers, 2018 to 2024). An acute inflammatory process that leads to necrosis of the pancreatic parenchyma. "We describe a case of recurrent acute pancreatitis due to homozygosity in APOA5 gene (c427delC, p.Arg143Alafs*57)." (PMID 38872171, 2024). "To summarize, this case report demonstrates a rare mutation in the APOA5 gene, which led to severe HTG, causing recurrent acute pancreatitis episodes in a young male." (PMID 38872171, 2024). "We here report a case of a young male in his 20 s with a frameshift mutation of APOA5 and severe HTG, who suffered from recurrent acute pancreatitis." (PMID 38872171, 2024). "One was the common APOA5 c.553G > T (p.Gly185Cys) variant, which has been previously associated with altered TG levels as well as HTG-induced acute pancreatitis (HTG-AP)." (PMID 34040631, 2021). "Chinese patients with HTG-associated acute pancreatitis (HTG-AP) were screened for rare nonsense, frameshift, missense or canonical GT-AG splice site variants in LPL and four other lipid metabolism-related genes (APOC2, APOA5, GPIHBP1 and LMF1) by Sanger sequencing." (PMID 37550668, 2023).
Hypercholesterolemia (6 papers, 2015 to 2025). An increased concentration of cholesterol in the blood.
Hypertension (6 papers, 2014 to 2024). The presence of chronic increased pressure in the systemic arterial system. "Although several researchers have reported that ApoA5 gene polymorphisms are closely related to vascular diseases like hypertension, coronary artery disease, and stroke, the fundamental underlying mechanism has not been investigated." (PMID 35941581, 2022). "The APOA5 polymorphisms were also identified to be implicated in regulation of blood pressure and in the development of hypertension in Japanese population." (PMID 24684850, 2014). "The goal of the study is to investigate the association between the APOA5 polymorphisms and haplotypes with Arterial Hypertension (AHT) in Moroccan patients." (PMID 24684850, 2014). "This regulation may contribute to the association between APOA5 and hypertension showed in this paper, but we cannot exclude other mechanisms." (PMID 24684850, 2014).
nonalcoholic fatty liver disease (6 papers, 2017 to 2025). "Although the role of ApoA5 in extrahepatic triglyceride (TG) metabolism in circulation has been well documented, the relationship between ApoA5 and nonalcoholic fatty liver disease (NAFLD) remains incompletely understood and the underlying molecular mechanism still needs to be elucidated." (PMID 38505614, 2024).
Stroke (5 papers, 2015 to 2025). Sudden impairment of blood flow to a part of the brain due to occlusion or rupture of an artery to the brain. "Genetic polymorphisms (e.g., APOA1 rs670, APOA5 rs662799) further complicate disease risk, showing population-specific associations with stroke and neurodegeneration." (PMID 40869228, 2025). "In contrast, certain APOA5 variants, notably rs651821, rs662799, and rs5069, show inconsistent associations with stroke and other neurological conditions." (PMID 40869228, 2025). "Among these SNPs, rs662799 is located in the promotor region of APOA5 gene, which is strongly associated with elevated TG levels, and confers risk for MetS and stroke." (PMID 26365620, 2015). "Similarly, the ApoA5 rs662799 polymorphism presents conflicting associations with ischemic stroke across different ethnic groups; while some studies identify the C-allele as protective, others associate it with elevated stroke risk." (PMID 40869228, 2025). "The rs2266788 polymorphism disrupts microRNA-3201 binding in the 3′ UTR of APOA5, increasing mRNA stability and expression, a potential pathway for dysregulated lipid metabolism in stroke or SCZ." (PMID 40869228, 2025).
Alzheimer disease (4 papers, 2020 to 2025). A progressive, neurodegenerative disease characterized by loss of function and death of nerve cells in several areas of the brain leading to loss of cognitive function such as memory and language. "In the recent genetic meta-analysis of Alzheimer’s disease, several genes were implicated in lipid processing, including APOM, APOA5, and ABCA1." (PMID 33166319, 2020).
hepatoma (4 papers, 2013 to 2019). "Previous studies have proved that both ApoA5 transgenic mice and hepatoma cells transfected with ApoA5 expression plasmid can lead to elevated TG accumulation in the liver." (PMID 31077206, 2019). "Knockdown of endogenous CREBH expression via small interfering RNA resulted in the downregulation of human APOA5 mRNA expression in human hepatoma cells, HepG2." (PMID 23957007, 2013).
ischemic stroke (4 papers, 2017 to 2025). A stroke disorder caused by obstruction of blood flow to the brain, due to thrombotic (local blood clot formation) or embolic (due to a blood clot or other material traveling from another site) event. "In conclusion, this study highlights significant interactions between dietary protein and fat intake and HDL-associated genetic variants, particularly the ABCA1 rs1883025 and APOA5 rs651821 variants, in modulating ischemic stroke and CAD risk, respectively." (PMID 40077648, 2025). "For instance, the rs662799 polymorphism in the APOA5 gene has been associated with an increased risk of ischemic stroke." (PMID 40869228, 2025). "The minor allele “C” of rs651821 in APOA5 was associated with a decreased ischemic stroke risk in the additive model (OR = 0.773; 95 % CI = 0.597 - 0.999; p = 0.040)." (PMID 28947988, 2017). "The haplotype “CGC” in APOA5 constructed by rs651821, rs662799 and rs17120035 in chromosome 11 was associated with a decreased ischemic stroke risk (OR = 0.770; 95 % CI = 0.595 - 0.997; p = 0.047)." (PMID 28947988, 2017). "APOA5-1131T/C (rs662799), as one polymorphism site of APOA5, has been widely studied in ischemic stroke susceptibility." (PMID 28947988, 2017). "For instance, ABCA1 rs1883025 T allele carriers may benefit from a high-protein diet to mitigate ischemic stroke risk, while APOA5 rs651821 carriers should be cautious about high-fat intake due to its potential to exacerbate CAD risk." (PMID 40077648, 2025). "For example, a study revealed that rs662799 and rs2266788 in the APOA5 gene can potentially impact the effectiveness of atorvastatin treatment in ischemic stroke patients by affecting different lipoprotein subfractions." (PMID 40869228, 2025). "We therefore performed a case-control study to investigate the associations between single nucleotide polymorphisms (SNPs) in APOA1, APOA5 and APOB, and the risk of ischemic stroke in Chinese Han population." (PMID 28947988, 2017). "To date, several independent studies suggest that APOA1, APOA5 and APOB levels are risk factors for ischemic stroke risk in Western populations." (PMID 28947988, 2017). "Human and animal data consistently show that the newly identified APOA5 gene may play an important role in the development of ischemic stroke and triglyceride metabolism." (PMID 28947988, 2017). "Four hundred eight patients with ischemic stroke and 347 unrelated healthy individuals of age and sex matched were genotyped for Apolipoprotein A5 (ApoA5), lipoprotein lipase (LPL), Cholesteryl ester transfer protein (CETP) and low-density lipoprotein receptor (LDL-R) genes." (PMID 28623937, 2017). "However, little is known about the contribution of APOA1, APOA5 and APOB genes polymorphisms to ischemic stroke risk, especially in the Chinese Han population." (PMID 28947988, 2017).
lipid metabolism disorder (4 papers, 2014 to 2024). "Previous studies suggested that apolipoprotein A5 (ApoA5) genetic polymorphisms (SNPs) may result in lipid metabolism disorders." (PMID 25515090, 2014). "In the current study, a positive correlation between serum ApoM and ApoA5 and HDL was observed, indicating that OSAHS might be involved in lipid metabolism disorder by regulating ApoM and ApoA5 on HDL." (PMID 27206623, 2017).
Sepsis (4 papers, 2020 to 2025). Sepsis is defined as life-threatening organ dysfunction caused by a dysregulated host response to infection. "Apolipoprotein A5 (ApoA5) regulates lipid metabolism and is reduced in pediatric sepsis, correlating with AKI risk due to microvascular dysfunction." (PMID 41296392, 2025). "PSP, copeptin, and APOA5 are promising diagnostic biomarkers for pediatric sepsis but inadequate predictors of mortality." (PMID 36755189, 2023). "To investigate the association of serum ApoA5 levels with sepsis-associated organ dysfunction precisely, we performed subgroup analysis among patients with sepsis." (PMID 32322166, 2020). "Serum ApoA5 level is associated with sepsis-associated shock, AKI, ALI, GI dysfunction, or MODS in children." (PMID 32322166, 2020). "A recent report in adult patients with sepsis indicated that low ApoA5 levels are associated with higher mortality, but the association became nonsignificant after adjusting for HDL-C levels." (PMID 32322166, 2020). "Consistently, a recent report in adult patients with sepsis indicated that low ApoA5 levels are associated with higher mortality." (PMID 32322166, 2020). "Furthermore, the serum ApoA5 level was significantly associated with septic shock, sepsis-associated liver injury, sepsis-associated AKI, and sepsis-associated GI dysfunction." (PMID 32322166, 2020). "Additionally, univariate logistic regression analysis indicated that a low ApoA5 level was an independent risk factor for PICU mortality in pediatric patients with sepsis (OR: 0.998, 95% confidence interval (CI): 0.996-0.999, P = 0.046)." (PMID 32322166, 2020). "The ROC assessment of the diagnostic power of the biomarkers and CRP showed that APOA5, copeptin and CRP levels had excellent AUC values (0.965, 0.960, and 0.917, respectively) for sepsis diagnosis." (PMID 36755189, 2023). "ApoA5 modulates triglyceride homeostasis, whilst elevated plasma triglycerides occur in the acute-phase of sepsis." (PMID 37456011, 2023). "The clinical values of serum ApoA5 in paediatric patients with sepsis were investigated; LPS-treated mice were used to assist the investigation." (PMID 37456011, 2023). "Serum levels of PSP, copeptin, and APOA5 were significantly higher in the pediatric sepsis group than in the control group." (PMID 36755189, 2023). "APOA5, copeptin, and PSP are acute-phase proteins with diagnostic value in evaluating critically ill pediatric patients with sepsis and detecting sepsis severity." (PMID 36755189, 2023). "Logistic regression analyses and receiver operating characteristic curve (ROC) analysis were used to investigate the potential role of serum ApoA5 as a prognostic predictor for PICU mortality in pediatric patients with sepsis." (PMID 32322166, 2020). "Given the potential role of ApoA5 in liver, kidney, and GI functions in patients with sepsis, we tried to evaluate the correlation of ApoA5 levels with the indicators for organ function." (PMID 32322166, 2020). "The serum ApoA5 level is associated with indicators of illness severity like shock, AKI, ALI, GI dysfunction, or MODS in pediatric patients with sepsis." (PMID 32322166, 2020). "In our present study, elevated serum ApoA5 levels were confirmed in pediatric patients with sepsis, which were significantly higher when compared with healthy children." (PMID 32322166, 2020). "Nevertheless, to the best of our knowledge, this is the first report about the serum ApoA5 level as a stable and powerful prognostic predictor in pediatric patients with sepsis." (PMID 32322166, 2020). "Subsequently, ApoA5 was evaluated in paediatric patients with sepsis." (PMID 37456011, 2023). "Given the important roles of the liver, kidney, or GI in lipid metabolism, serum ApoA5 levels mainly might be related to the metabolic stress during sepsis." (PMID 32322166, 2020). "All these results suggested that ApoA5 as an acute-phase protein responding to infection could be an additional biomarker for sepsis." (PMID 32322166, 2020).